CCNJ (cyclin J)
Synonyms: FLJ10895; bA690P14.1
Tractability: No criterion of Open Targets' tractability assessment is met for any kind of drug.
Gene: Protein-coding gene on chromosome 10 (96,043,394 to 96,060,870, forward strand). Ensembl gene ENSG00000107443.
Subcellular location (Human Protein Atlas): Cytosol
Gene Ontology:
Molecular function: cyclin-dependent protein serine/threonine kinase regulator activity
Cellular component: cyclin-dependent protein kinase holoenzyme complex; microtubule organizing center
Genetic constraint (gnomAD): Loss-of-function variants: 12 observed, 39.12 expected, observed/expected ratio (o/e) 0.31, 90% interval 0.2 to 0.5. The upper end of that interval is the gene's LOEUF score, 0.5, which puts it in group 2 of 6, group 1 being the genes least tolerant of losing a copy. Missense variants: 340 observed, 478.52 expected, observed/expected ratio (o/e) 0.71, 90% interval 0.65 to 0.78. Synonymous variants: 160 observed, 176.46 expected, observed/expected ratio (o/e) 0.91, 90% interval 0.8 to 1.03.
Homologues: Orthologues: macaque CCNJ (100% identical), chimpanzee CCNJ (99% identical), pig CCNJ (99% identical), rabbit CCNJ (98% identical), rat Ccnj (96% identical), mouse Ccnj (96% identical), guinea pig CCNJ (79% identical), tropical clawed frog ccnj (77% identical), zebrafish ccnj (63% identical), Drosophila melanogaster CycA (18% identical), Drosophila melanogaster CycB (17% identical), Caenorhabditis elegans cya-1 (16% identical), and 9 more. Paralogues in human: CCNJL (44% identical), CCNA2 (20% identical), CCNA1 (19% identical), CCNB2 (18% identical), CCND1 (17% identical), CCND2 (17% identical), CCNB1 (17% identical), CCNI (17% identical), CCNO (16% identical), CCND3 (16% identical), CCNF (16% identical), CCNE2 (15% identical), and 6 more.
Diseases named in the same sentence as CCNJ in open-access papers:
CCNJ is named in the same sentence as 13 diseases in open-access papers, as found by Europe PMC text mining. Sharing a sentence is not in itself a finding about the gene and the disease. The quoted sentences say what the papers report.
breast carcinoma (5 papers, 2013 to 2017). "Importantly, CCNJ expression is present in 20% of patients with breast cancer, exclusively in the malignant tissues." (PMID 24098452, 2013). "In consistent with these reports, miR-125b was found to exert its anti-tumor activity via regulating ENPEP (aminopeptidase A), CK2-α (casein kinase 2 alpha), CCNJ (cyclin J) and MEGF9 (multiple EGF-like-domains 9) in breast cancer." (PMID 25605244, 2015). "Apart from the overexpression of ENPEP, CK2-α, CCNJ, and MEGF9 in certain breast cancer patients, the potential oncogenic roles of these proteins is supported by the fact that their downregulation causes significant inhibition of cell proliferation." (PMID 24098452, 2013). "To investigate the importance of ENPEP, CK2-α, CCNJ, and MEGF9 proteins in breast tumors, we studied the expression of each protein by western blot analysis in 25 breast cancer patient samples (series 3)." (PMID 24098452, 2013). "Analysis of ENPEP, CK2-α, CCNJ, and MEGF9 protein expression in breast cancer patients revealed that they were overexpressed in 56%, 40–56%, 20%, and 32% of the tumors, respectively." (PMID 24098452, 2013). "Finally, we analyzed the protein expression of ENPEP, CK2-α, CCNJ, and MEGF9 in breast cancer patients." (PMID 24098452, 2013). "In particular, our results show that restoration of miR-125b expression or knockdown of ENPEP, CK2-α, CCNJ, or MEGF9 may provide novel approaches for the treatment of breast cancer." (PMID 24098452, 2013). "In addition, correlation analysis between miR-125b levels (analyzed with qRT-PCR) and the expression of ENPEP, CK2-α, CCNJ, and MEGF9 protein was studied in 25 breast cancer patient samples (series 3)." (PMID 24098452, 2013). "Our data suggest that in some percentage of patients with breast cancer tumors, miR-125b downregulation consistently occurs; this involves a repression of the genes that code for ENPEP and CK2-α, and potentially MEGF9 and CCNJ." (PMID 24098452, 2013). "Glutamyl aminopeptidase (ENPEP), casein kinase II subunit α (CK2-α), cyclin J (CCNJ), and multiple epidermal growth factor-like-domains 9 (MEGF9) are additional miR-125b targets that are upregulated in human breast cancer samples and may contribute to tumor progression." (PMID 24774301, 2014).
bladder cancer (3 papers, 2015 to 2025). "CCNJ, the cyclin J, controls the G2/M cell cycle transition and has been implicated as oncogene in different tumors, such as breast and gastric cancer, bladder cancer, and non-small cell lung cancer." (PMID 39858538, 2025). "So the levels of CCNJ expression were examined in bladder cancer cell lines 5637, T24, J82 and SW780, and in normal urinary tract HCV29 cells." (PMID 26469956, 2015). "Mechanistic studies using bladder cancer cells T24 overexpressed with miR-205 further revealed the modulation of CCNJ expression by miR-205." (PMID 26469956, 2015). "We found that CCNJ was highly expressed in bladder tissues and bladder cancer cells, indicating that CCNJ may also participate in the bladder tumorigenesis." (PMID 26469956, 2015). "Also in bladder cancer, cyclin J (CCNJ), a member of the cyclin family, has been detected to be aberrantly expressed." (PMID 26469956, 2015). "In bladder cancer, the HOTAIR/miR-205/CCNJ (cyclin J) axis has been shown to promote growth, whilst HOTAIR silences the tumor suppressive miR-205 by disrupting the balance of histone modifications on the miRNA promoter." (PMID 29702599, 2018).
gastric cancer (3 papers, 2017 to 2025). A primary or metastatic malignant neoplasm involving the stomach. "Similarly, through modulating cyclin J (CCNJ) and far upstream element-binding protein 1 (FUBP1), exogenous expression of miR-16 could reverse the resistance to trastuzumab and lapatinib in HER2 positive gastric cancer cells." (PMID 32192494, 2020).
hepatocellular carcinoma (2 papers, 2024 to 2025). A malignant tumor that arises from hepatocytes. "The CpG site cg04590978 influences the methylation of the CCNJ gene, which is associated with prognosis in hepatocellular carcinoma." (PMID 40177272, 2025). "The methylation of specific genes, including VASH2, CHFR, GRID2IP, CCNJ, SEPT9, and F12, is considered a biomarker for the onset of hepatocellular carcinoma (HCC)." (PMID 38473997, 2024).
acute leukemia (1 paper, 2017). A clonal (malignant) hematopoietic disorder with an acute onset, affecting the bone marrow and the peripheral blood. "A previous study also indicated that CCNJ could be a novel prognostic marker of HCC and acute leukemia (ALM)." (PMID 28202053, 2017).
acute lymphoblastic leukemia (1 paper, 2013). Leukemia with an acute onset, characterized by the presence of lymphoblasts in the bone marrow and the peripheral blood. "CCNJ is a putative oncogene because is embedded in a cluster of genes found dysregulated in pediatric high-risk B-precursor acute lymphoblastic leukemia." (PMID 24098452, 2013).
breast tumors (1 paper, 2013). "The aim of analyzing ENPEP, CK2-α, CCNJ, and MEGF9 expression in breast tumors was to clarify their association with miR-125b." (PMID 24098452, 2013).
urothelial bladder cancer (1 paper, 2017). "MiR-205 targets the cell-cycle regulation gene cyclin J (CCNJ) and is proved relevant to the inhibition of proliferation, migration, and invasion of the urothelial bladder cancer cell lines." (PMID 28231804, 2017).
tumor (10 papers, 2013 to 2023). "In contrast, miR-16 acts as a tumor suppressor and can restore trastuzumab and lapatinib sensitivity by suppressing Cyclin J (CCNJ) and Far Upstream Element Binding Protein 1 (FUBP1) in resistant BC." (PMID 32967267, 2020). "It was found that miR-16 inhibited cell proliferation in BC cell lines and in tumor samples resistant to these drugs; this suggested a tumor suppressor role for miR-16, as it targets CCNJ (Cyclin J) and FUBP1 (Far Upstream Element Binding Protein 1)." (PMID 28574440, 2017). "Moreover, up-regulation of miR-146a led to a significant decrease of CCNJ in tumor tissues, as determined by RT-qPCR, western blot and IHC, respectively." (PMID 28202053, 2017). "In its tumor-suppressive functions, miR-125b has been reported to target ENPEP, CK2-α, CCNJ, MEGF9 or the proto-oncogene ETS1." (PMID 25633049, 2015). "miR-125b was found to perform its tumor suppressor function via the direct targeting of the 3’-UTRs of ENPEP, CK2-α, CCNJ, and MEGF9 mRNAs." (PMID 24098452, 2013). "MiR-125b also exhibited good anti-tumor effects in murine orthotopic breast cancer, which was attributed to its promotive effect on M1 polarization by targeting interferon regulatory factor 4 (IRF4) in macrophages, and suppressed tumor cells by targeting ETS proto-oncogene 1 and cyclin-J." (PMID 37138859, 2023).
cancer (4 papers, 2013 to 2020). A tumor composed of atypical neoplastic, often pleomorphic cells that invade other tissues. "Regarding the lack of an association between miR-125b and CCNJ expression, it is tempting to hypothesize that miR-125b may correlate with CCNJ levels in certain tumorigenic cells (e.g., cancer stem cells)." (PMID 24098452, 2013). "miR-146a induces cell cycle arrest at the G0/G1 phase and thereby suppresses the proliferation of cancer cells in the lung and increases cisplatin sensitivity by targeting JNK2 and cyclin J." (PMID 33294082, 2020). "The relevance of ENPEP, CK2-α, CCNJ, and MEGF9 proteins in cancer is gradually being revealed." (PMID 24098452, 2013).
CCNJ also shares sentences with these, for which no sentence is quoted: non-small cell lung carcinoma (2 papers); prostate carcinoma (2); bladder (1).